HMOX1 (heme oxygenase 1)
Diseases named in the same sentence as HMOX1 in open-access papers (continued):
Sharing a sentence is not in itself a finding about the gene and the disease.
ulcerative colitis (23 papers, 2015 to 2025). An inflammatory bowel disease involving the mucosal surface of the large intestine and rectum. "The anti-inflammatory effect of a single HBO application was further evident through the downregulation of HMOX1, primarily implicated in a multitude of inflammatory diseases (i.e., Crohn’s disease and ulcerative colitis)." (PMID 37887323, 2023).
gastric ulcer (22 papers, 2008 to 2025). An ulcerated lesion in the mucosal surface of the stomach. "Previous studies have indicated associations between ethanol-induced gastric ulcer elevations in inflammatory cytokines, such as interleukin-1β (IL-1β), interleukin-6 (IL-6), heme oxygenase-1 (HO-1), and tumor necrosis factor-α (TNF-α)." (PMID 39064740, 2024). "Benzyl isothiocyanate (BITC) can regulate inflammation, oxidative stress, and apoptosis through the nuclear factor erythroid 2-related factor 2 (Nrf2)/heme oxygenase-1 (HO-1) and NF-kB signaling pathways, thus exerting anti-gastric ulcer effects." (PMID 39517291, 2024). "Two pivotal targets, heme oxygenase 1 (HMOX1) and albumin (ALB), are believed to assume a significant role in the treatment of gastric ulcers by the construction of “compounds-target-metabolite” networks." (PMID 38259271, 2023).
Hepatitis (22 papers, 2016 to 2026). Inflammation of the liver. "For the hepatitis network, important identified pathways were, again, mainly involved in responses to increased oxidative stress, which initiates cytoprotective action of upregulated HMOX1 leading to mitochondrial dysfunction associated with downregulation of the SLC6A6 taurine transporter." (PMID 35865277, 2022). "Lansoprazole has been reported to provide hepatoprotection in a drug-induced hepatitis animal model through the Nrf2/heme oxygenase-1 (HO1) pathway." (PMID 37384717, 2023).
Hyperbilirubinemia (22 papers, 2009 to 2025). An increased amount of bilirubin in the blood. "However, little is known regarding the clinical impact of the HMOX1 variants on neonatal hyperbilirubinemia." (PMID 25102181, 2014). "A retrospective case control study of breast-fed full-term infants was carried out to determine whether variants in Uridine Diphosphate Glucuronosyl Transferase 1A1 (UGT1A1) and Heme Oxygenase-1 (HMOX1) were associated with neonatal hyperbilirubinemia." (PMID 25102181, 2014). "Hyperbilirubinemia and liver heme oxygenase-1 (HO-1) induction in lipopolysaccharide (LPS)-treated rats resulted in a 2-fold accumulation of tissue UCB, which was associated with enhanced protection against lipid peroxidation." (PMID 34573106, 2021). "Human serum albumin (HSA) or heme oxygenase-1 (HO-1) inhibitor SnPP (Tin protoporphyrin IX dichloride) was injected intraperitoneally into Ugt1−/− mice to establish a treatment model for endogenous hyperbilirubinemia." (PMID 34527681, 2021). "Further research effort in Indonesia is warranted to investigate other potential genetic factors in different pathways leading to hyperbilirubinemia, including BLVRA and HMOX1." (PMID 31253110, 2019).
osteosarcoma (22 papers, 2018 to 2026). A usually aggressive malignant bone-forming mesenchymal neoplasm, predominantly affecting adolescents and young adults. "When HMOX1 was upregulated, it resulted in ferroptosis in the osteosarcoma cells and had the exact opposite effect when HMOX1 was knocked down, thus showing its involvement in ferroptosis." (PMID 40508028, 2025). "For instance, osteosarcoma cells display high expression of HMOX1, so EF24, which promotes HMOX1 expression, can be employed to expedite ferroptosis in these cells." (PMID 38475936, 2024). "Five ferroptosis-associated genes (MUC1, MAP3K5, LURAP1L, HMOX1, and BNIP3) correlated with the prognosis of osteosarcoma were screened for the construction of the risk score model." (PMID 36899330, 2023). "In osteosarcoma, zoledronic acid can induce ferroptosis by decreasing ubiquinone and upregulating the expression of HMOX1 or cytochrome P450 oxidoreductase (POR)." (PMID 37388742, 2023). "EF24, a synthetic analogue of curcumin, induced ferroptosis through up-regulating HMOX1 in osteosarcoma cells." (PMID 36838613, 2023). "Further studies are required to delineate which of these factors mediates zoledronic acid-induced increase in HMOX1 mRNA expression in osteosarcoma cells." (PMID 36686696, 2022). "Zoledronic acid treatment significantly enhanced HMOX1 protein and mRNA levels in osteosarcoma cells." (PMID 36686696, 2022). "In summary, our study demonstrates for the first time that zoledronic acid inhibits the growth of osteosarcoma cells by inducing ferroptosis through reducing cellular CoQ10 content and upregulation of HMOX1 expression." (PMID 36686696, 2022). "Our result also indicates that zoledronic acid induces ferroptosis in osteosarcoma cells by promoting a rise in HMOX1 protein and mRNA level." (PMID 36686696, 2022). "Similarly, the curcumin synthetic analog EF24 has been reported to induce ferroptosis in osteosarcoma by upregulating HMOX1 and increasing MDA and ROS levels." (PMID 40790027, 2025). "Moreover, particular metabolites such as zoledronic acid induce iron-induced death in osteosarcoma cells by reducing coenzyme Q levels and stimulating heme oxygenase 1(HMOX1)expression." (PMID 40098980, 2025). "Moreover, HMOX1 overexpression induces ferroptosis by suppressing GPX4 expression in osteosarcoma cells." (PMID 39857625, 2024). "However, the expression of HMOX1 was lower in osteosarcoma tissues, which was in line with the prediction of Kaplan-Meier survival curve." (PMID 37285835, 2023). "It remains to be determined whether zoledronic acid and EF24 activate the same or different pathway to upregulate HMOX1 in osteosarcoma cells." (PMID 36686696, 2022). "In osteosarcoma cells, the derivative EF24 activates heme oxygenase 1 (HMOX1) in a dose-dependent manner while suppressing GPX4 expression, resulting in increased intracellular levels of MDA, ROS, and Fe2+." (PMID 41515171, 2025). "In the present study, we analyzed the high-throughput RNA-sequencing data and clinical information of 86 osteosarcoma patients, and identified eight prognosis-related genes, including MAP3K5, G6PD, HMOX1, ATF4, ACADVL, MAPK1, MAPK10, and INS." (PMID 37285835, 2023). "In this study, we found significant differences between the prognosis of patients with low and high expression levels of ACADVL, ATF4, HMOX1, INS, and MAPK10, indicating that these genes are potential therapeutic targets of osteosarcoma." (PMID 37285835, 2023). "MAP3K5, LURAP1L, HMOX1 and BNIP3 expression levels were markedly decreased in the osteosarcoma cells compared with the normal human osteoblast hFOB1.19 cells, they are negatively related with the riskscore." (PMID 36899330, 2023). "A recent study shows that HMOX1 expression mediates ferroptosis induction by EF24, a synthetic analogue of curcumin, in osteosarcoma cells." (PMID 36686696, 2022).
endotoxemia (21 papers, 2004 to 2025). "Nuclear factor erythroid 2-related factor (Nrf2) has been identified as a key regulator of the expression of antioxidant proteins, including heme oxygenase-1 (HO-1), which protects against endotoxemia." (PMID 41169942, 2025). "Modulation of the heme oxygenase-1 (HO-1) pathway can offset oxidative stress, improve myocardial function in endotoxemia, and increase survival rates in septic mice." (PMID 40364840, 2025). "Gelam honey inhibited lipopolysaccharide-induced endotoxemia in rats through the induction of heme oxygenase-1 and the inhibition of cytokines, nitric oxide and high-mobility group protein B1." (PMID 33435215, 2021). "A possible/plausible regulator of this phenomenon is heme oxygenase-1 (HO-1), which is induced by LPS and provides defense against endotoxemia, including LPS-induced ARF, controlling the IL-6/IL-10 balance." (PMID 24376813, 2013). "It has been recently reported that raloxifene, a selective ER modulator, reduces the effects of LPS-induced endotoxemia in ovariectomized rats via the induction of antioxidant and anti-inflammatory proteins such as heme oxygenase 1 (HO-1) and heat shock protein 70 (HSP70), respectively." (PMID 29925409, 2018).
oral cancer (21 papers, 2014 to 2025). "NRF2, TXN, and HMOX1 genes were downregulated by fucoidan treatment in oral cancer, causing oxidative stress." (PMID 36139851, 2022). "Pomegranate extract also downregulates NFE2L2, TXN, CAT, SOD1, and HMOX1 gene expressions in oral cancer cells and induces oxidative stress." (PMID 36139851, 2022). "BioMed Research International has retracted the article titled “Involvement of Nrf2-Mediated Upregulation of Heme Oxygenase-1 in Mollugin-Induced Growth Inhibition and Apoptosis in Human Oral Cancer Cells”." (PMID 32908872, 2020). "Similarly, pomegranate extract (POMx) downregulates mRNA expressions of the NRF2, TXN, and HMOX1 genes to induce oxidative stress in oral cancer Ca9-22 cells." (PMID 35624705, 2022). "In the present study, EANT generates oxidative stress, which is accompanied by mRNA overexpression for antioxidant genes (NFE2L2, CAT, HMOX1, and TXN) in oral cancer cells." (PMID 34575651, 2021). "Accordingly, the antioxidant signaling gene expression for mRNA, including NFE2L2, GCLC, TXN, CAT, SOD1, HMOX1, and NQO1, was examined for POMx-incubated oral cancer cells." (PMID 34356350, 2021). "In response to oxidative stresses, the mRNA for antioxidant signaling, such as nuclear factor erythroid 2-like 2 (NFE2L2), catalase (CAT), heme oxygenase 1 (HMOX1), and thioredoxin (TXN), are overexpressed in oral cancer cells." (PMID 34575651, 2021). "Similar to the present study, the mRNA expressions for several antioxidant genes (NFE2L2, GCLC, TXN, CAT, SOD1, HMOX1, and NQO1) were downregulated at 24 h POMx for three oral cancer cell lines." (PMID 34356350, 2021). "These oxidative stress effects were attributed to the downregulation of antioxidant signaling genes (NRF2, TXN, and HMOX1) in oral cancer cells rather than S–G cells." (PMID 35624705, 2022). "Antioxidant genes (NRF2, TXN, and HMOX1) were downregulated in fucoidan-treated oral cancer cells but not in non-malignant oral cells." (PMID 35624705, 2022). "Consistently, we found that low concentrations of WFA induced mRNA expressions of NFE2L2, HMOX1, and NQO1 genes, which may lead to inhibitory migration of oral cancer cells." (PMID 32429564, 2020).
pancreatitis (21 papers, 2009 to 2026). Inflammation of the pancreas. "We observed a trend towards an enrichment of S-alleles in AP and ACP, but this finding is counterintuitive as the S-allele has been associated with more HMOX1 activity and thereby probably protects against the development of pancreatitis." (PMID 22666428, 2012). "In conclusion, our results implicate that HMOX1 variants are unimportant in different forms of pancreatitis and ALC." (PMID 22666428, 2012). "As such, it is reasonable to portend that different GT-repeat alleles or other HMOX1 genetic alterations contribute to the pathogenesis of different pancreatitis phenotypes." (PMID 22666428, 2012). "As rare non-synonymous HMOX1 variants were found in patients and controls, it is rather unlikely that they will have functional consequences essential for pancreatitis development." (PMID 22666428, 2012). "In addition, smoking represents a risk factor for pancreatitis and HMOX1 alterations seem to influence the susceptibility to smoking related disorders." (PMID 22666428, 2012). "As such, HMOX1 variants might be of importance in the pathogenesis of pancreatitis." (PMID 22666428, 2012). "Induction of Heme-oxygenase-1 (HO-1) improves the survival of pancreas grafts by prevention of pancreatitis after transplantation in a rat model of pancreas transplantation with HO-1 induction with cobalt protoporphyrin." (PMID 36902067, 2023). "Although data obtained in experimentally induced AP picture HMOX1 as a potential target in pancreatitis, we cannot further support this view on the basis of our genetic case control study." (PMID 22666428, 2012). "In animal models of experimental pancreatitis, expression of HMOX1 is up-regulated in pancreatic islet and acinar cells and HMOX1 as well as carbon monoxide (CO) act protective." (PMID 22666428, 2012). "In animal models, elevated Hmox1 expression ameliorates the course of pancreatitis." (PMID 35741777, 2022). "As such, our data probably rule out that HMOX1 promoter variants modulate the risk for pancreatitis of any aetiology." (PMID 22666428, 2012). "In animal models the course of pancreatitis was ameliorated by up-regulation of HMOX1 expression." (PMID 22666428, 2012). "To investigate the role of HMOX1 alterations in pancreatitis, we extensively screened the GT-repeat, SNP rs2071746, and the coding sequence in up to 446 patients with different forms of pancreatitis, 147 patients with alcoholic liver cirrhosis (ALC) and up to 413 healthy controls." (PMID 22666428, 2012). "The current study investigates the influence of genetic HMOX1 alterations in different types of pancreatitis since there is evidence that HMOX1 induction might influence the development and the course of AP and the pathogenesis of CP by inhibition of PSC proliferation." (PMID 22666428, 2012). "Therefore, the role of HMOX1 coding variants in other disease forms unlike pancreatitis is not thoroughly clarified." (PMID 22666428, 2012). "Reportedly, the upregulation of IL-10 in the model of pancreatitis, along with the inhibition of TNF-α, was induced by heme oxygenase-1 (HO1)." (PMID 34122596, 2021).
steatosis (21 papers, 2015 to 2025). Increased lipid within the cytoplasm of cells. "The results of our study have led to the identification of six compounds that induce HMOX1 expression and exhibit protective effects against oxidative stress and steatosis in vitro, highlighting their potential as therapeutic agents for NAFLD." (PMID 37507903, 2023). "Notably, the identified compounds in our study, particularly Auranofin, demonstrated strong induction of HMOX1 expression and protective effects against oxidative stress and steatosis in vitro." (PMID 37507903, 2023). "Macrovesicular steatosis (P = 0.016), donor body mass index (P = 0.013), recipients' pretransplant serum creatinine (P = 0.036), and intrahepatic expression of heme oxygenase 1 (HO1) (P = 0.015) and tumor necrosis factor α (TNF-α) (P = 0.039) were independent predictors of EAD." (PMID 34957150, 2021). "To investigate the potential of the identified HMOX1 inducers in this study to ameliorate NAFLD, we set up an in vitro steatosis assay using HUH-7 cells." (PMID 37507903, 2023).
ischemia reperfusion injury (20 papers, 2011 to 2025). Adverse functional, metabolic, or structural changes in ischemic tissues resulting from the restoration of blood flow to the tissue (reperfusion), including swelling; hemorrhage; necrosis; and damage from free radicals. "The stress-responsive enzyme heme oxygenase-1 (HO-1) is known to prevent ischemia-reperfusion injury (IRI), which is a main cause of AKI." (PMID 32655407, 2020). "Administering genetically altered macrophages that express heme-oxygenase-1 (HO1) offered kidney protection to mice undergoing ischemia-reperfusion injury." (PMID 38740765, 2024). "Organ transplantation inevitably results in ischemia-reperfusion injury, hemolysis, and heme release, which induces Heme oxygenase-1 (HO1) expression." (PMID 38517040, 2024). "Among enzymes activated by NrF2, heme oxygenase-1 (HO-1) is a promising therapeutic target for ischemia-reperfusion injury (IRI) due to its abundant antioxidant response elements (AREs) in its promoter region." (PMID 38024816, 2023). "Accordingly, depletion of endogenous antioxidants and upregulation of the endogenous antioxidant enzyme heme oxygenase-1 (HO-1) accompanies ischemia reperfusion injury (IRI), and drugs that ameliorate oxidative stress can attenuate IRI." (PMID 26379029, 2015).
nonalcoholic fatty liver disease (20 papers, 2013 to 2025). "The liver Cu deficiency plays a role in the pathogenesis of diseases such as nonalcoholic fatty liver disease, bile duct ligation-induced liver injury, fibrosis, inhibited ceruloplasmin activity, and disturbed heme oxygenase-1 gene expression." (PMID 30746586, 2019). "Similarly, Eriodictyol exhibits the potential to ameliorate nonalcoholic fatty liver disease (NAFLD) by modulating autophagy mediated by ubiquitin A‐52 (UBA52) and upregulating the Nrf2/HO‐1 (heme oxygenase‐1) signaling pathway to attenuate oxidative stress." (PMID 39554371, 2024).
psoriasis (20 papers, 2016 to 2024). An autoimmune condition characterized by red, well-delineated plaques with silvery scales that are usually on the extensor surfaces and scalp. "It has been observed that while the levels of iron and TIBC (Total iron-binding capacity) were significantly lower in psoriasis patients compared to healthy donors, Soluble transferrin receptor (sTfR) and Heme Oxygenase-1 (HO-1) were over-expressed." (PMID 38827737, 2024). "The nuclear factor erythroid 2–related factor 2 (Nrf2) and its regulators were increased in both forms of psoriasis while heme oxygenase 1 levels were increased only in psoriasis vulgaris." (PMID 30301214, 2018). "The expression of HMOX1 is induced by Nrf2 in many cell types, including proliferating keratinocytes, under conditions of oxidative stress, and Nrf2-dependent HO-1 expression has also been reported for the inflammatory skin disease psoriasis." (PMID 37755285, 2023). "Although there have been studies on HMOX1 expression in the skin and linking the over-expression of HMOX1 to dermatological disorders, such as psoriasis and atopic dermatitis, and to systemic diseases, such as systemic lupus erythematosus, no studies have yet investigated HMOX1 in DLE." (PMID 37507892, 2023). "Modification of the cytosolic Nrf2 inhibitor—Keap1 protein—prevents the formation of a complex with Nrf2 and promotes its transcriptional activity, leading to the biosynthesis of cytoprotective proteins, such as heme oxygenase 1 (HO-1), as observed in psoriasis." (PMID 35208171, 2022). "The expression of HMOX1 can be induced by a variety of stimuli, including the proinflammatory cytokines TNF and IL17, which are abundant in the lesional skin of psoriasis patients." (PMID 34575702, 2021). "The stress-response enzyme heme oxygenase-1 (HO-1) has been described as protective in animal models of psoriasis, however, implementation of HO-1-based therapies is hindered by the lack of clinically-suitable HO-1 inducers." (PMID 29980703, 2018).